HIPK2 (homeodomain interacting protein kinase 2)
Diseases named in the same sentence as HIPK2 in open-access papers (continued):
Sharing a sentence is not in itself a finding about the gene and the disease.
tumor (continued). "Chromosome counts of metaphase spreads showed a clear prevalence of near-tetraploid karyotypes in the E1A/Ras Hipk2−/− tumors at opposite with Hipk2+/+ tumor cells, that were mostly in the diploid range, suggesting that aneuploid cells are not counter-selected in vivo, during tumor formation." (PMID 25868975, 2015). "However, recent reports also indicate that HIPK2 can stimulate cell growth and that its expression level correlates with tumour progression." (PMID 23805307, 2013). "Previous reports described HIPK2 as a tumour suppressor responsive to DNA damage." (PMID 23805307, 2013). "HIPK2 has been described as a potential tumour suppressor and DNA damage-responsive kinase." (PMID 23805307, 2013). "Restoration of tumor cell chemosensitivity was also reported in another study showing that exogenous HIPK2 overexpression was able to circumvent inhibition of apoptosis in cisplatin-resistant ovarian cancer cells although the molecular mechanism is still elusive." (PMID 22889244, 2012). "For these reasons, HIPK2 is a promising biomarker and a target for tumor therapy." (PMID 22889244, 2012). "Our results indicate that HIPK2 expression and function are impaired in WDTCs, in particular in PTCs, and that this event explains Gal-3 overexpression typically observed in these types of tumours." (PMID 21698151, 2011). "HIPK2 may represent a new tumour suppressor gene for these types of cancers and may constitute a new potential promising diagnostic marker and therapeutic target." (PMID 21698151, 2011). "Interestingly, HIPK2 decreased expression at mRNA and protein level was observed in all the cases of FVPTCs, suggesting a relevant role of HIPK2 in this tumour type." (PMID 21698151, 2011). "Other molecular events, distinct from 7q34 duplication, may lead to HIPK2 overexpression and may account for increased HIPK2 levels in tumours other than JPA." (PMID 19603027, 2009). "Homeodomain-interacting protein kinase-2 (HIPK2) plays an essential role in restraining tumor progression as it may regulate, by itself or within multiprotein complexes, many proteins (mainly transcription factors) involved in cell growth and apoptosis." (PMID 18644116, 2008). "HIPK2 overexpression in tumor cells downregulated VEGF mRNA levels and VEGF promoter activity." (PMID 18644116, 2008). "However, given its pleiotropic role, including a well-established tumor suppressive function, a complete blockade of HIPK2 as a long-term therapeutic approach in CKD may yield unwanted side effects." (PMID 38512421, 2024).
tumor (continued). "Interestingly, hypoxia has been shown to downregulate HIPK2 through Siah-2-dependent proteasomal degradation, allowing the induction of a substantial fraction of hypoxia-induced genes, therefore, controlling tumor progression and response to therapies." (PMID 39062921, 2024). "Since HIPK2 has been shown to repress the vimentin gene promoter, one of the most important markers of EMT, and to restrain the cancer cell invasion, it is tempting to speculate that HIPK2 inhibition by the HG condition might also contribute to promoting tumor invasion." (PMID 37345014, 2023). "Furthermore, whether therapy resistance dependent on HG-induced inhibition of HIPK2 activity is universal or specific for certain tumor types remains largely unexplored." (PMID 37345014, 2023). "These basic functions of HIPK2 may explain its key role in several biological processes, including development, fibrosis, angiogenesis, and neurodegeneration, as well as its function as a “bona fide” tumor suppressor." (PMID 37345014, 2023). "The expression and role of HIPK2 may differ depending on tumor site and histological type." (PMID 36289359, 2022). "In summary, our results provide new information supporting the already well-established tumour suppressor role of HIPK2, and also could explain how under certain conditions (for example, cancer cell chemoresistance due to upregulated NRF2) HIPK2 might provide cancer cells with a survival advantage." (PMID 28692050, 2017). "Therefore, HIPK2 may decrease tumor invasion and metastasis through its regulation of JNK signaling pathways." (PMID 28107201, 2017). "Finally, the contributions of HIPK2 to tumor regression and the response to anticancer drugs suggest that HIPK2 might be a diagnostic marker and a therapeutic target." (PMID 27689990, 2016). "However, when the size of nuclear areas was quantified on a subset of randomly selected tumor regions by using morphometric software, we found that the mean nuclear area of mononucleated Hipk2−/− tumor cells was significantly higher than that of Hipk2+/+ tumor cells." (PMID 25868975, 2015). "Thus, it is important to identify HIPK2 as one of the CIN genes with different tumor-protective molecular activities, because it might facilitate to decipher the basis of heterogeneity of HIPK2 dysfunctions in different tissues and subsets of cancers." (PMID 25868975, 2015). "Therefore, HIPK2 activity is considered a central switch in targeting tumor cells toward apoptosis upon genotoxic damage and the preservation and/or restoration of HIPK2 function is crucial for an efficient tumor response to therapies." (PMID 22889244, 2012). "In this regard, HIPK2 is often inactivated in tumors by multiple mechanism such as gene downregulation, gene mutation, protein mislocalization as well as by protein degradation through MDM2 or hypoxia-induced factors, impairing the cellular response to drug and supporting tumor progression." (PMID 19828042, 2009). "In addition, the malignant phenotype was shown in HIPK2 heterozygous mice, suggesting that HIPK2 may restrain tumor development and progression by acting on multiple different but sometime interconnected pathways." (PMID 19828042, 2009).
tumor (continued). "In conclusion our findings support the potential role of HIPK2 as oncosuppressor and might give important contributions for the development of novel combinatory anti-tumoral therapeutical approaches focused to deal with tumor angiogenesis." (PMID 18644116, 2008). "Correlation with tumor progression and TNM stages;HIPK2 knockdown reduces ERK phosphorylation in vitro and the growth of tumors derived from KRAS mutated cells." (PMID 39062921, 2024). "In mutant KRAS-carrying colon cancer cells, HIPK2 depletion impairs phosphorylation of extracellular signal-regulated kinases 1 and 2 (ERK1/2) and tumor growth in a xenograft model." (PMID 39342278, 2024). "On the other hand, in KIRP, CDK1, CDK4, HIPK2 and MYC expression increased with the pathological and clinical stage of the tumor, whereas KLF4 decreased." (PMID 37047552, 2023). "As a proof of principle, HIPK2 silencing with small interfering RNA upregulated HIF-1α in cancer cells, inducing a pseudohypoxic tumor phenotype in normoxic conditions, fueling tumor progression, and chemoresistance." (PMID 36900356, 2023). "To dissect the dynamic changes of both kinases and phosphoproteins in PDAC, we performed kinase–substrate enrichment analysis (KSEA), and four kinases (HIPK2, ROCK1, PRKCD, MAPKAPK2) were identified as tumor-specific activated." (PMID 36434634, 2022). "This study also showed a high expression of HIPK2 in RA; more importantly, overexpression of HIPK2 abrogated the action of miR-129-5p in RA-FLS tumor-like biologic behaviors." (PMID 33964939, 2021). "HMGB1 expression was inversely correlated with HIPK2 and HMGB1 physically interacted with HIPK2 both in tumor or non-tumor tissues." (PMID 33747917, 2021). "Our results have uncovered a new downstream effector of HIPK2, NRF2, which is frequently activated in human tumours correlating with chemoresistance and poor prognosis." (PMID 28692050, 2017). "In a hypoxic environment, HIPK2 down-regulates the activity of HIF-1, Siah1, Siah2, VEGF and WBS-1 to inhibit tumor angiogenesis." (PMID 28107201, 2017). "Here, we investigated the therapeutic potential of the imbalance between Hipk2-Δe8 and Hipk2-FL isoforms induced by e8-siRNA#1 in a series of CRC cells including patient-derived tumor-initiating cells (i.e., Cancer Stem Cells – CSCs)." (PMID 26625198, 2016). "Homeodomain interacting protein kinase 2 (HIPK2) is a member of an evolutionary conserved family of serine/threonine kinases, which is considered as a tumor suppressor gene and mediates the activation of Wnt, Notch, and TGF-β-induced signaling." (PMID 25421593, 2015). "In the present study, it was proposed that the HIPK2-mediated inhibition of HIF-1α correlated with the suppression of MDR1 gene transcription and the sensitization of cobalt-treated tumor cells to adriamycin-induced apoptosis." (PMID 24137413, 2013). "This included genes in which upregulation is implicated in cancer (CTDSP2, CASC3, PGF) and those that are thought to be involved in tumor suppression (SASH1, HIPK2)." (PMID 23406646, 2013). "In this regard, HIPK2 knockdown induces HIF-1α upregulation with increased HIF-1 activity leading to vascular endothelial growth (VEGF) production, tumor angiogenesis and chemoresistance." (PMID 23144866, 2012). "The authors further showed using an immunohistochemical approach that overexpression of HIPK2 was more frequent in LGA than in high-grade gliomas, and that it was more common in infratentorial tumours." (PMID 19603027, 2009). "We showed that HIPK2 down-regulated both endogenous VEGF mRNA levels and the VEGF levels induced by β-catenin overexpression, in different tumor cells, highlighting interplay between HIPK2-mediated β-catenin regulation and VEGF expression." (PMID 18644116, 2008).
tumor (continued). "Many different mechanisms can contribute to VEGF up-regulation and in this regard we have recently found that HIPK2 can regulate the HIF-1α-induced VEGF expression, inhibiting tumor angiogenesis (L.N. and G.D.O. unpublished results)." (PMID 18644116, 2008). "↑ Tumor progression and TNM stages;↓ HIPK2 expression reduces ERK phosphorylation in vitro." (PMID 39062921, 2024). "HIPK2 overexpression reduces the basal levels of HIF-1α with a mechanism that does not involve hypoxia, inhibiting the HIF-1 transcriptional activity and, therefore, counteracting theHIF-1-induced angiogenesis and tumor progression, in vitro and in vivo." (PMID 37345014, 2023). "Our previous studies showed that HIPK2 binds, along with histone deacetylase 1 (HDAC1), to the HIF-1α gene promoter repressing the HIF-1-mediated transcription of many target genes including VEGF, therefore restraining tumor growth." (PMID 36900356, 2023). "HIPK2 promotes the degradation of HIF-1α, suppressing tumor growth and progression of HCC." (PMID 35629368, 2022). "IHC analysis of C-terminal HIPK2 expression showed negative staining (–) in 50% of 64 tumor samples, weak staining (+) in 39.1%, moderate staining (++) in 9.4%, and strong staining (+++) in 1.6%." (PMID 33613845, 2021). "However, in the current study blood expression changes in HIPK2 and PPP1CC identify those participants with significant anti-tumour transcriptomic responses to supplementation in the rectum." (PMID 34340708, 2021). "When HIPK2 and miR-1260b were assessed according to the TNM stage (early stages I + II vs. late stages III + IV), HIPK2 was decreased and miR-1260b was enhanced, regardless of the tumor stage." (PMID 34321461, 2021). "Immunohistochemistry (IHC) analysis of N-terminal HIPK2 expression in human NSCLC showed negative staining (–) in 1.3% of 78 tumor samples, weak staining (+) in 9.0%, moderate staining (++) in 37.2%, and strong staining (+++) in 52.6%." (PMID 33613845, 2021). "IHC analysis of N-terminal HIPK2 expression in human normal lung tissues showed negative staining (–) in 21.1% of 90 tumor samples, weak staining (+) in 78.9%, moderate staining (++) in 0%, and strong staining (+++) in 0%." (PMID 33613845, 2021). "HIPK2 plays a dual role in cancers by either functioning as a tumour suppressor or facilitating tumour progression, suggesting that HIPK2 is a positive effector or a negative effector of apoptosis." (PMID 30154452, 2018). "As HIPK2 is a tumor suppressor and mediator of DNA damage-induced apoptosis, our results propose a new measure to improve the efficiency of genotoxic cancer therapies possibly by interfering with the PARP1 WGR-HIPK2 interaction." (PMID 27787517, 2016). "Inhibition of miR-30a induced significant upregulation of BNIP3L, PRDM9, and SEPT7, while inhibition of miR-934 increased the expression of HIPK2, HOXA4, and MLL3, suggesting that the miRNAs exert negative regulatory effects on these established tumor suppressors." (PMID 26472042, 2015). "For instance, HIPK2 knockdown induces upregulation of oncogenic hypoxia-inducible factor-1 (HIF-1) activity leading to a constitutive hypoxic and angiogenic phenotype with increased tumor growth in vivo." (PMID 23144866, 2012). "Collectively, the data presented in this study indicated that HIPK2 could repress the β-catenin transcription activity and downregulate VEGF expression in tumor cells." (PMID 18644116, 2008).
tumor (continued). "Interestingly the 15q-induced HIPK2 inhibition does not affect HIPK2 anti-tumor activity, underscoring selective HIPK2 targeting as an anti-fibrosis drug." (PMID 36831402, 2023). "IHC analysis of the xenograft tumor tissues derived from Huh7 or BEL-7404 cancer cells, with or without HIPK2 overexpression, showed that HIPK2 downregulation significantly increases VEGFα level in the subcutaneous tumor and in the corresponding new blood vessels." (PMID 36900356, 2023). "HIPK2 can phosphorylate β-catenin for proteasomal degradation and such degradation leads to the transcriptional impairment of several β-catenin target genes, including the vascular endothelial growth factor (VEGF) involved in tumor angiogenesis and tumor growth." (PMID 36831402, 2023). "In addition, we identified that regulation of some of the tarGenes (e.g., PRX, HIPK2, and PPARD) may be important for tumor progression." (PMID 30424545, 2018). "For instance, HIPK2 has been shown to serve as a transcriptional coactivator in the Smad2/3/4-SBE reporter assays and in JNK-mediated functions, which critically regulate the decision of survival and apoptosis in dopaminergic neurons and in tumor cells, respectively." (PMID 23565059, 2013). "Subsequent studies demonstrated that HIPK2 phosphorylates β-catenin for proteasomal degradation, thus interfering with the transcription of several β-catenin target genes, including vascular endothelial growth factor (VEGF) involved in tumor angiogenesis and tumor growth." (PMID 22889244, 2012). "Thus, HIPK2 inhibition by RNA interference induces HIF-1α up-regulation and tumor angiogenesis." (PMID 19714248, 2009). "Recent study suggest that circRNA-homeodomain-interacting protein kinase-2 (circHIPK2) may act as an endogenous miR-506-3p sponge, leading to an increase in σ-1R27, whereas its host gene-HIPK2 is involved in cell growth modulation, apoptosis, proliferation and tumor progression." (PMID 29238093, 2017). "Our findings obtained both in tumor cells and in non-transformed RPE-1 cells show that HIPK2 depletion induces MBR accumulation, whereas depletion of the two known HIPK2 cytokinesis targets, Spastin and ecH2B, has only a marginal effect in MBR accumulation." (PMID 33043004, 2020). "However, it is likely that the effects of HIPK2 are quite different between tumor cells and non-tumor cells and HIPK2 inhibitors could be used in CKD patients without history of cancers using the same criteria that we currently use for immunosuppressive medication in patients with kidney disease." (PMID 25972814, 2015).